MITF (melanocyte inducing transcription factor)
Diseases named in the same sentence as MITF in open-access papers (continued):
Sharing a sentence is not in itself a finding about the gene and the disease.
melanoma (continued). "Although we did not perform statistical analyses on the three transitory melanoma cell lines, TNFα clearly reduced both MITF and Melan A levels and concurrently increased NGFR and AXL expression in this melanoma subtype." (PMID 34073253, 2021). "Like the proinvasive receptor tyrosine kinase AXL, EGFR is expressed in dedifferentiated melanoma cells in a negative correlation with the melanocytic lineage factor MITF." (PMID 33916908, 2021). "We focused on gene signatures specific for single-cell populations with low MITF, (i) a subpopulation of cells which represent minimal residual disease (MRD) in melanoma, a small population of cells that remain upon drug treatment and (ii) an invasive gene signature." (PMID 33438577, 2021). "Using a gene therapeutic approach, we demonstrated silencing of HuR reduced MITF protein expression and inhibited the growth of melanoma cells but not normal melanocytes." (PMID 33418925, 2021). "Melanomas are usually immunoreactive for Melanoma antigen recognized by T-cells-1 (MART-1) or melan A, S-100 protein, melanoma-specific antigen (HMB-45), tyrosinase, and Microphthalmia transcription factor (MITF)." (PMID 34209084, 2021). "At the transcriptional level, MITF controls genes involved in cell survival (BCL2, HIF1A, BCL2A1), migration (DIAPH1, MET) and proliferation (CDK2, TBX2, CDKN1B), providing important signals for growth of melanoma cells." (PMID 34289891, 2021). "However, the specific TF MITF of skin cutaneous melanoma (SKCM), which is a marker of melanoma cell differentiation and regulates a variety of melanocyte differentiation genes." (PMID 34712617, 2021). "In a recent study, Melanocyte Inducing Transcription Factor (MITF) and EGFR genes have shown the highest frequency of genomic amplification, with a lower rate in primary melanomas as compared to metastatic melanomas, considering both tumor tissues and cell lines." (PMID 34123788, 2021). "In melanoma cells, β-catenin activates proteins involved in melanogenesis and pigmentation such Melan-A, dopachrome tautomerase (DCT) and tyrosinase, all through MITF." (PMID 34356645, 2021). "Cells lacking MITF are similar to the cells of minimal residual disease observed in both human and zebrafish melanomas." (PMID 33438577, 2021). "We confirmed that SB202190, but not BIRB796, elicits nuclear translocation of the MITF-A isoform in melanoma cells (see Figshare file, “Subcellular localisation of MITF”)." (PMID 33802847, 2021). "Based on relative expression of transcription factors like MITF and SOX10, six interconvertible distinct states were discovered recently: undifferentiated, NC stem cell (NCSC), intermediate, starved melanoma cell (SMC), melanocytic-like and the hyperdifferentiated/pigmented state." (PMID 33870460, 2021). "In this case, the high OXPHOS phenotype was shown to rely on mitochondrial transcription factor A (TFAM), but not PGC1α, indicating that some melanoma cells adopt an elevated mitochondrial phenotype independent of the MITF-PGC1α signalling axis." (PMID 34830962, 2021). "In the absence of fibroblasts, melanoma differentiation is driven by collagen stiffness via the YAP/PAX3/MITF axis." (PMID 33922284, 2021). "This showed that expression of PXN was specifically induced in MITFlow melanoma cell lines and displayed a negative correlation with MITF expression." (PMID 33438577, 2021). "MITF has not been implicated in OSA but is amplified, is a driver gene in human melanoma via the RAS/MEK pathway, and MITF inactivation leads to chemosensitivity." (PMID 33556121, 2021). "To further elucidate the inhibitory mechanism, we investigated the effect of VP on the SRY (sex determining region Y)-box 10 (SOX10) and paired box gene 3 (PAX3) transcription factors that regulate melanoma markers such as protein melan-A (MART-1) and MITF expressed in melanoma cells." (PMID 33672928, 2021).
melanoma (continued). "Immunohistochemistry and single-cell sequencing studies of melanoma tumors have shown the existence of cells with low or no MITF expression." (PMID 33438577, 2021). "Moreover, resistance to MAPK inhibitors can be overcome by mTORC1/2 through the nuclear exclusion of MITF, and this combination has a synergistic effect only in the OXPHOS-high phenotype of melanomas." (PMID 34073463, 2021). "Since MITF induced the proteolytic cleavage of NKG2D ligands, we next examined the activity of NK cells against melanoma cells lacking MITF." (PMID 33789714, 2021). "Moreover, in melanoma cell lines, extracellular acidosis induces upregulation of AXL receptor tyrosine kinase and reduction in MITF expression, which leads to the appearance of MITFlow/AXLhigh phenotype." (PMID 33918883, 2021). "Then, we showed that adenovirus-forced MITF expression led to an increase in FBXO32 protein expression in both 501MEL and A375 melanoma cell lines, while MITF silencing decreased the expression of FBOX32 and DCT, a known transcriptional target of MITF in MeWo and 501Mel cell lines." (PMID 33462405, 2021). "Triple MITF/SOX10/SOX11 co-expression was seen in 9 out of 15 negative conventional pan-melanoma-cocktail cases." (PMID 33801642, 2021). "Additionally, oncogenes that can be regulated by epigenetic modifiers and support melanoma progression and development include RAS, ERK, c-jun, MITF, MDM2, and BCL-2." (PMID 34944799, 2021). "The MET gene in melanoma is regulated by PAX3, SOX10 and MITF." (PMID 33807778, 2021). "Overexpression of miR-182 stimulates melanoma cell migration and invasion through the direct downregulation of MITF and FOXO3 expression; studies on melanoma cell lines and tissue samples have found that its expression increases gradually from primary to metastatic stage." (PMID 33203119, 2020). "As MITF‐positive and MITF‐negative tumors are known to harbor different transcriptional programs and presumably represent two distinct melanoma states, we thus performed subsequent analyses in MITF‐positive and MITF‐negative tumors separately." (PMID 32147909, 2020). "Osteoblast‐derived RANKL stimulates MITF‐driven tolerance to MAPK inhibition, which may contribute to the increased resistance to targeted therapies observed in melanoma patients with metastatic bone lesions." (PMID 31323160, 2020). "Here we investigated the cross-regulatory relationship of MITF and TFEB in melanoma cells." (PMID 32881934, 2020). "The number of melanomas removed was higher in MITF+ compared to MITF− negative patients: 27% of the MITF+ patients have removed more than 2 melanomas versus 11% of the MITF− patients (p = 0.03)." (PMID 32054529, 2020). "The number of genes with significantly positive or negative correlation with MITF expression in lung adenocarcinoma and melanoma." (PMID 33293474, 2020). "The dissociation of the HINT1-MITF complex can also be induced in melanoma cells through post-translational modification of HINT1 residues surrounding the MITF-HINT1 interface, which may allow prolongation of MITF-controlled processes." (PMID 33282915, 2020). "Since TYR and TYRP1 are MITF target genes, we interrogated previously published ChIP-seq datasets to determine if BRD4 and MITF co-occupy MITF-binding sites at the TYR and TYRP1 loci in melanocytes and melanoma cells." (PMID 32151278, 2020). "It has been reported that MAPK inhibitor-resistant SK-MEL-28 cells have a decreased expression ratio of melanocyte-inducing transcription factor (MITF) to AXL receptor tyrosine kinase, a marker of targeted therapy resistance in melanoma, which is possibly driven by increased ATF4 expression." (PMID 33396632, 2020).
melanoma (continued). "Our data suggest that MITF activates LTR5_Hs in melanoma (not in melanocytes); thus, Rec expression specifically marks the proliferative type of melanoma cells." (PMID 33202765, 2020). "Phenotypically, MITF downregulation via CREB signaling has been reported to provoke melanogenesis blockage affecting cell viability and body pigmentation in B16F10 murine melanoma cells and zebrafish model, respectively." (PMID 33126560, 2020). "Hence, it is not surprising that the mTORC1/2 inhibitor AZD8055, which triggers MITF cytoplasmic retention, was able to decrease PGC1α expression and OXPHOS in melanoma." (PMID 33202944, 2020). "Taken together, these results have suggested dominant roles for BRN2 in melanoma progression and invasion that are independent of MITF." (PMID 32632141, 2020). "In B16F10 murine melanoma cells stimulated with the melanocyte hormone α-MSH, AL inhibited phosphorylation of PKA and CREB and downregulated protein expression of tyrosinase and MITF." (PMID 32120828, 2020). "Although drug-naïve melanoma cells were either AXLhigh/MITFlow or AXLlow/MITFhigh, their drug-resistant counterparts while losing expression of MITF did not become AXLhigh." (PMID 31936151, 2020). "Thus, the conclusion that the inverse correlation exists between MITF-positive and NGFR-positive cells cannot be applied for all melanomas developing drug resistance." (PMID 31936151, 2020). "We propose that a better understanding of MITF and immune system intersections could help in the tailoring of current ICT in melanomas and pave the way for clinical benefits and long-lasting responses." (PMID 33276788, 2020). "In order to investigate the role of MITF with respect to melanoma development in varying RHC background, HA-tagged MITF was introduced via lentiviral transduction in both the WT MC1R Hermes 3C and in the compound heterozygote MC1R R160W/D294 Hermes 4C melanocytes." (PMID 32605315, 2020). "Although it is well known that LEF1 usually involves melanocyte differentiation and phenotype switching by increasing microphthalmia-associated transcription factor (MITF), the pro-survival role of LEF1 in melanoma is not fully understood." (PMID 32933177, 2020). "This suggests that MITF and BRD4 are also likely to interact in melanocytes and melanoma cells." (PMID 32151278, 2020). "Indeed, ZEB1 and TWIST1 have been shown to downregulate MITF whereas SNAIL2 or ZEB2 induce MITF expression, demonstrating that these EMT-TFs act as key players in melanoma phenotype switching." (PMID 32858889, 2020). "We found that ABCB5 was differentially co-expressed in a cluster of 0D5P cells with the transcription factor MITF and CTNNB1, whose expression may be enriched in melanoma stem-cell populations." (PMID 32157095, 2020). "Several studies have previously shown that the expression of melanogenic enzymes (tyrosinase, TRP-1, and TRP-2) is transcriptionally regulated by MITF, resulting in a decrease in melanogenic enzyme expression and the inhibition of melanogenesis in B16F10 melanoma cells." (PMID 32630811, 2020). "MITF lacks specificity, so it is not beneficial for use in differentiating epithelioid melanomas from carcinomas but does have the advantage of being expressed in the nucleus, making the interpretation of IHC easier to read." (PMID 33339193, 2020). "MITF and SOX10 suppress expression of DIRC3, which potentially contributes to melanoma development." (PMID 33329688, 2020). "The BRAFi prohibitive signalling from osteoblasts was however, unable to elicit protection in MITF negative melanoma cells (SKMEL105), indicating that intact MITF expression is required for osteoblast induced protection." (PMID 31323160, 2020).
melanoma (continued). "In addition, MITF-positive cells expressed the melanoma cell adhesion molecule (MCAM/CD146), which was initially identified as a marker of melanoma progression and metastasis, and MCAM expression was regulated by MITF." (PMID 33371469, 2020). "MITF has been shown to serve as a sensitive and specific marker for distinguishing melanoma from histologically similar nonmelanocytic tumors." (PMID 32429485, 2020). "Furthermore, the effects of BEA and BEA G1 were associated with the suppression of multiple molecular targets that play crucial roles in melanoma oncogenesis, including ERK, JNK, p38, NF-κB, STAT3, and MITF." (PMID 32340351, 2020). "Given that MITF has roles in DNA repair, ITH and the expression of differentiation antigens, a comprehensive understanding of its role in these processes is a major asset to better understand melanoma resistance to immunotherapies." (PMID 33276788, 2020). "Of note, MITF, with which SAMMSON is co-amplified at 3p13-3p14, is a transcriptional regulator of lncRNA DIRC3, which is disrupted by balanced translocations in renal carcinoma and suppressed by SOX10 in melanoma cells (see Translocations)." (PMID 33329688, 2020). "As such, MITF upregulation, following MAPK inhibition, appears to function through an adaptive response, leading to a micro-environment, which can support the outgrowth of a sub-population of melanoma cells." (PMID 31416288, 2019). "Finally, the AM404 + GSK126 combination, after O/N treatment, reversed the EMT-like profile of melanoma cells by reducing SNAIL, ZEB1, AXL, and α-catulin protein expression while upregulating MITF and E-cadherin." (PMID 30710146, 2019). "Next, in silico ChIP-seq analyses revealed binding of MITF to an E box (tCACGTG) consensus sequence −86 base pairs upstream of the transcriptional start site of CDK7 in primary melanocytes, primary melanoma and melanoma cell lines." (PMID 30651597, 2019). "Additionally, we treated mouse melanoma cell line B16F10 with 0, 50, and 500 ng/mL of bovine GH (bGH) for 24 and 48 h and analyzed the change in expression of MITF and a number of MITF target genes." (PMID 31547367, 2019). "Therefore, during the progression in melanoma patients with BRAF inhibitors, the expression of melanoma antigens was dramatically decreased along with downregulation of MITF." (PMID 31134073, 2019). "To screen for potential MITF target genes coding for general transcription and nucleotide excision repair (NER) factors, we analyzed transcriptome data on a panel of primary and metastatic melanomas, melanoma in situ and melanocytes (GSE7553)." (PMID 30651597, 2019). "Melanoma cells have been shown to be “addicted” to MITF and thus the NRAS*-mediated downregulation of MITF could cooperate with the upregulation of SPRY4 to suppress growth." (PMID 30651601, 2019). "MITF-mediated MET upregulation is known to elicit antiapoptotic effects in melanocytes and melanoma, while our earlier reports did show a GH-mediated increase in MET levels in human melanoma." (PMID 31547367, 2019). "Although we observed a mild increase in either PRL or PRLR in the human melanoma cell lines due to doxorubicin, we did not observe any upregulation of MITF or MITF targets due to PRL addition." (PMID 31547367, 2019). "In 57% of the melanoma cell lines tested, the consequent increase in ERK activity lead to proteolytic degradation of its substrate, the lineage specific transcription factor MITF, likely contributing to growth arrest." (PMID 31040916, 2019). "Indeed a decrease in the level of Ubiquitin Ligase RNF125 has been described to correlate with SOX10/MITF expression and to promote BRAF inhibitors resistance in melanoma." (PMID 31118886, 2019). "To ask whether a deregulated TCA cycle could be responsible for the pseudo‐hypoxia signature observed in some MITF‐low melanoma cell lines, we first confirmed that both malonate and succinate can lead to elevated HIF protein levels in melanoma cells." (PMID 31207090, 2019).
melanoma (continued). "In addition, SFX significantly suppressed the levels of a transcription factor MITF, which can increase the expression of late endosomal proteins, such as RAB7 and CD63, and a main sEV secretion regulator, RAB27a, in melanoma cells." (PMID 30918259, 2019). "SOX10 predominantly occupies distal (non-promoter) enhancer regions in melanocyte and melanoma genomes, colocalizes with MITF at enhancers, and interacts with BRG1 at melanocyte-specific enhancer regions." (PMID 31399133, 2019). "Immunohistochemical analyses of melanoma patients with differential response to DNA-alkylating chemotherapy agents dacarbazine or temozolomide identified high MITF and melanosomal protein levels in the nonresponsive group." (PMID 31547367, 2019). "In a reciprocal experiment, forced expression of MITF in MITF-negative A375 melanoma cells augmented basal transcriptional activity and transcriptional recovery after UVR." (PMID 30651597, 2019). "The results showed that SAB298 suppressed MITF levels in four out of seven melanoma cell lines (YUSIV, YUSIK, SK-MEL-28 and YUKIM), but not in YUPEET, YUSEEP and 501 mel cells." (PMID 31040916, 2019). "In agreement with our hypothesis, in silico ChIP-seq analyses identified occupancy of MITF at proximal E box containing promoter sequences of FUBP2 (KHSRP) in primary melanocytes and melanoma cell lines." (PMID 30651597, 2019). "This hypothesis was driven, in part, by our previous data in human melanoma cells, in which knockdown of GDF6 decreased phospho-SMAD1/5/8 binding at the MITF locus and increased MITF expression." (PMID 31868592, 2019). "In melanoma, PGC-1α expression is in turn controlled via the transcription factor MITF." (PMID 30841515, 2019). "MITF expression was dramatically reduced in C8-infected Mel501 and SK28 melanoma cells." (PMID 30674989, 2019). "To test if DIRC3 is a MITF and SOX10 regulated target gene we first used multiple different siRNAs to deplete these two transcription factors in 501mel, SK-MEL-28 and A375 human melanoma cell lines, and measured changes in DIRC3 expression using RT-qPCR." (PMID 31881017, 2019). "As BRN2 represses MITF and drives motility of tumor cells in vivo, the BRN2-MITF expression axis may be considered as a driver of melanoma invasion, in addition to TGFβ, JARID1B and β-catenin signalings." (PMID 31118886, 2019). "In the TCGA melanoma dataset, the top 312 genes with a positive correlation (down to Spearman r = 0.5) with the prototypic EMT marker ZEB1, were also positively correlated with SNAI1, NFATc2, CDH2, and AXL, but negatively with MITF and CDH1." (PMID 30710146, 2019). "For example, Melanocyte Inducing Transcription Factor (MITF) is either overexpressed or amplified in about 13% of cases and is shown to be important for melanoma progression and is a lineage survival oncogene in malignant melanoma." (PMID 31217906, 2019). "We could confirm the correlation of MITF with BRN2 and PAX3 expression at RNA level and at protein level in a panel of melanoma cell lines." (PMID 30277012, 2019). "However, we discovered a novel role for YAP in melanoma, where it acts as cofactor for PAX3-driven expression of MITF, thereby regulation not only proliferation but also differentiation." (PMID 29545604, 2018). "In aggregate, lowering of MITF levels alone generally does not lead to EMT‐like phenotype patterns on Western blots in six melanoma cell lines." (PMID 29369499, 2018). "Since we also detected MITF and its target gene tyrosinase (TYR) to be regulated upon modification of canonical Wnt signaling in SKMEL28 melanoma cells it could be that MITF is at least partially involved in the pro-migratory effects in vitro and in vivo." (PMID 29454361, 2018). "At the initial stage of drug treatment, SOX10 may provide rapid protection on melanoma cells by upregulating pro-survival factors such as FOXD3, MITF, and SAMMSON and therefore is important for the survival of melanoma cells." (PMID 29295999, 2018).